CTTN (cortactin)
Diseases named in the same sentence as CTTN in open-access papers (continued):
Sharing a sentence is not in itself a finding about the gene and the disease.
cancer (continued). "Downregulation of cortactin in cancer cell lines decreases the cellular motility and ability to migrate whereas overexpression resulted in an increased invasive potential." (PMID 18268491, 2008). "Gene by gene functional analyses have revealed that cyclin D1, FADD and cortactin are potentially able to enhance cancer development." (PMID 18268491, 2008). "The cortactin gene CTTN (formerly EMS1) resides on chromosome locus 11q13 that is frequently amplified in human cancers, including over 30% HNSCCs." (PMID 18268492, 2008). "Cortactin is a substrate of c-Src, and activation of Src family tyrosine kinases is known to be critically involved in carcinoma cell migration extracellular matrix degradation and invasive behaviour." (PMID 18268492, 2008). "This region of chromosome 11 contains several genes, most notably CyclinD1 and ESM1/Cortactin, which are frequently overexpressed, mainly through amplification, in a variety of human cancers." (PMID 16552434, 2006). "Gene amplification of 11q13 region and concomitant overexpression of cortactin frequently occurs in several human carcinomas and correlates with lymph node metastasis and increased mortality." (PMID 15710041, 2005). "High cortactin expression has been observed in multiple cancers, including CC." (PMID 41148856, 2025). "Cortactin seems to mediate these cancer cells activities via ARP2/3 activation." (PMID 40328105, 2025). "Additionally, previous studies reported that ESCC-associated proteins, including PCNA, SLC7A5, CTTN, RB1, EGFR, TP63, and PRMT1, exhibited increased expression in S-III; among these proteins, SLC7A5 and EGFR were FDA-approved drug targets for cancer treatment." (PMID 38652547, 2024). "Therefore, CAFs-derived SLIT2 increased the expression and phosphorylation levels of CTTN, which induced cytoskeletal reorganization and led to the acquirement of excessive migratory capacities of cancer cells." (PMID 37443302, 2023). "The location of the CTTN gene on chromosome 11q13, a region frequently amplified in OSCC and associated with worse prognosis, further supports its significance for this type of cancer." (PMID 37623256, 2023). "Furthermore, we showed that hAM homogenate slightly reduced the cortactin expression in both cancer urothelial cell lines." (PMID 37932474, 2023). "There are several reports that overexpression of CTTN can induce resistance to anti-cancer drugs." (PMID 36831511, 2023). "Furthermore, the motility of cancer cells was reduced following the expression of an acetylated mimetic mutant of CTTN, while motility was increased when the cells expressed a deacetylation mimetic mutant." (PMID 35562995, 2022). "In cancer cells, deacetylation of CTTN was increased when SIRT1 levels were high." (PMID 35562995, 2022). "Hypermethylation of UCHL1 promotes cancer metastasis and downregulates CTTN degradation; however, it remains unclear how these CTTN ubiquitination PTMs relate to lung cell function or disease." (PMID 35562995, 2022). "Cortactin is an important regulator of cancer cell motility and mesenchymal movement." (PMID 33407452, 2021). "Additionally, potassium channels have been described to contribute to cancer cell invasion via their interaction with molecules associated with invadopodia formation, such as focal adhesion kinase (FAK), integrins, and cortactin." (PMID 33050088, 2020). "Therefore, a variety of components, such as Cortactin, Caveolin-1, Tks4/5, and protein tyrosine kinase Src of invadopodia, are usually used as indicators to gauge the mobility and invasion potentials of cancer cells in vitro and in vivo system." (PMID 32033570, 2020). "Importantly, the amplification of the cortactin gene (CTTN) is evident in a number of cancers, correlating with enhanced tumor invasiveness and poor prognosis." (PMID 33050088, 2020). "Not surprisingly, dysregulation of CTTN expression caused by post-translation modification can contribute to the pathogenesis of human diseases, including cancer." (PMID 32120844, 2020).
cancer (continued). "Cortactin induces the EMT in other types of cancer and promotes tumorigenesis." (PMID 33195233, 2020). "Phosphorylated cortactin activates the Arp2/3 complex to mediate a mechanism by which cancer cells might facilitate actin filamentation and branching while remodeling the extracellular matrix to gain increased motility and invasiveness." (PMID 32620753, 2020). "The proposed influence of ion channels on actin cytoskeletal rearrangement and various proteins including cortactin and integrins may contribute to mechanisms mediating invadopodia formation and activity in cancer cells." (PMID 33050088, 2020). "Silencing of cortactin and Tks proteins dramatically inhibits cancer cell extravasation." (PMID 31167468, 2019). "In addition, we stained for Vimentin (VIM), which is a marker for epithelial-mesenchymal transition in cancer cells, and cortactin." (PMID 31804471, 2019). "This may provide an opportunity for cancer treatment by inhibition of kinases that regulate cortactin or by disruption of protein interactions with the SH3 domain of cortactin." (PMID 30976201, 2019). "Cortactin is an important regulator involved in the invasion and migration of cancer cells." (PMID 29986736, 2018). "Moreover, verifying the significance of the PTPN1/cortactin pathway in cell metastasis of other cancers is needed." (PMID 29743988, 2018). "However, more insight is required to clarify the functions of cortactin in tumor progress and the tumor microenvironment, the binding domains of cortactin in promoting the aggressiveness of cancer cells." (PMID 29152154, 2017). "CTTN is a cytoskeletal protein involved in coordinating actin reorganization during cell movement and is overexpressed in numerous cancers where it may contribute to cell invasion." (PMID 28174229, 2017). "An intensive study of the cortactin role in tumor may lead to identifying some new therapeutic strategies to treat cancer." (PMID 29152154, 2017). "In summary, cortactin is crucial for many cancer cellular processes." (PMID 29152154, 2017). "To ascertain whether CTTN could promote cancer cell proliferation, we labeled cancer cells with the thymidine analog EdU after siRNA pool transfection to monitor the activity of DNA synthesis." (PMID 27903975, 2017). "Thus, in addition to over-expression and tyrosine phosphorylation, alternative splicing of the F-actin binding domain of cortactin which influences cell migration is one important mechanism contribute to the etiology of cancer." (PMID 28404950, 2017). "However, further studies are required to make clear the mechanization of the chromosome 11q13 amplification and cortactin overexpression in cancer cells." (PMID 29152154, 2017). "Finally, we reviewed reports that cortactin is overexpressed in many cancers through 11q13 amplification." (PMID 29152154, 2017). "In addition, a recent study indicated that ezrin binds to another actin-binding protein, cortactin, in cancer cells to promote formation of podosomal rosettes, which digest underlying fibronectin and promote invasion." (PMID 29291001, 2017). "Six proteins 60Sacidic ribosomal protein P2, Peroxiredoxin-2, Annexin A5, PDZ and LIM domain protein 1, Src substrate cortactin and Moesin were found as emerging proteins of the H22 cell incubated with high dose lentinan which related to cancer promotion closely." (PMID 29221118, 2017). "Our research demonstrated that asporin might promote cancer cell invasion by targeting the EGFR/Src/cortactin signaling pathway." (PMID 27705916, 2016). "This implicates that a strategy to reduce the cortactin expression in other malignant neoplasms might also be helpful to improve prognosis and survival time." (PMID 27911942, 2016). "Using cancer cell lines with naturally occuring high levels of this integrin, activation by α9β1-specific ligands led to upregulation of fibronectin matrix assembly and tyrosine phosphorylation of cortactin on tyrosine 470 (Y470)." (PMID 27339664, 2016).
cancer (continued). "Cortactin is a multi-domain protein that was first identified as a Src substrate and subsequently shown to be involved in a variety of cellular processes, including cancer progression, invasion and metastasis." (PMID 26166158, 2015). "The nuclear translocation of cortactin in cancer cells was a new observation." (PMID 26134506, 2015). "Cortactin phosphorylation and its functional consequences have been well studied with multiple reports documenting a correlation between high levels of tyrosine phosphorylation and elevated cell migration and cancer metastasis." (PMID 26166158, 2015). "Cortactin is an important factor involved in cancer cell progression and invasion." (PMID 26134506, 2015). "Thus, cortactin is used as a marker for detection of invadopodia and enrichment of cortactin indicates the metastatic level in a number of cancers." (PMID 26134506, 2015). "Similarly, phosphorylated cortactin is also able to initiate actin assembly but to form invadopodia in cancer cells, followed by extracellular matrix (ECM) degradation." (PMID 26134506, 2015). "Cortactin overexpression results from the 11q13.3 chromosomal region amplification in various cancers, such as head and neck squamous carcinoma, hepatocellular carcinoma, breast and bladder cancer, and correlates with poor patient prognosis and decreased survival." (PMID 24465712, 2014). "However, the role of Hax-1 in cancer cell migration or its role in Rac1-cortactin complex formation, which is known to be required for such migration remains to be characterized." (PMID 25053987, 2014). "The phosphorylated form of cortactin (pTyr421) is required for cancer cell motility and invasion." (PMID 24465712, 2014). "CTTN gene amplification in cancer has previously been reported." (PMID 24523870, 2014). "CTTN gene is amplified and its protein is overexpressed in several types of cancer." (PMID 24465712, 2014). "Apart from cancer embolus and distant metastasis, it is worth noting that liver capsule integrity may be the latent correlation factor to cortactin expression, though the P values were 0.054." (PMID 23518204, 2013). "In addition, it has been well documented that CTTN is amplified in several other human cancers leading to cortactin overexpression." (PMID 23518204, 2013). "Many studies have documented a role for cortactin in promoting cell motility and cancer invasion." (PMID 21998723, 2011). "AMAP1 functions by binding to cortactin in cancer invasion and metastasis." (PMID 21858086, 2011). "The involvement of Src-catalyzed cortactin phosphorylation in cell motility control suggests cortactin might be a crucial regulator of cancer metastasis." (PMID 22078467, 2011). "On the other hand, cortactin overexpression might induce an increase in the invasive potential affecting later stages of cancer development (this study)." (PMID 18268491, 2008). "Thirdly, in human cancer overexpression of cortactin is correlated with metastasis formation." (PMID 16536875, 2006). "In human carcinomas, overexpression of cortactin correlates with poor prognosis." (PMID 15710041, 2005). "Moreover, cortactin was proven as a substrate for Src, which is often highly expressed in cancer." (PMID 41158752, 2026). "In addition, cortactin, a substrate of Src family tyrosine kinases, is responsible for invadopodia assembly by regulating the F-actin-enriched invadopodia cytoskeleton to promote cancer migration, invasion, vessel penetration, and metastasis." (PMID 36835419, 2023). "However, the precise mechanism by which cortactin could be utilized to target cancer metastasis must be further investigated." (PMID 30976201, 2019). "In PDAC, an invasive cancer with high metastatic potential, remodeling of the actin cytoskeleton, changes in cell–cell adhesions, and enhanced migratory potential all might be based on cortactin-mediated actin dynamics." (PMID 30976201, 2019).
cancer (continued). "Therefore, it is plausible that Hakai may also influence the migratory capabilities that are important for the dissemination of cancer cells by its action on cortactin localization." (PMID 29472634, 2018). "Because ABL kinase inhibitors significantly decrease cortactin phosphorylation-mediated actin polymerization as well as matrix degradation in treated invasive cancer cells, we hypothesized that they might also control the ability of the cells to invade through an extracellular matrix barrier." (PMID 29774130, 2018). "We mapped the HS1BP3-cortactin interaction site to the third proline-rich region (PRR3.1) of HS1BP3 and show that this interaction is important for cancer cell proliferation, extracellular matrix degradation and secretion." (PMID 41960636, 2026). "The HCLS1-Binding Protein 3 (HS1BP3) interacts with the SH3 domain of cortactin (CTTN), a protein that contributes to a malignant phenotype in cancers." (PMID 41960636, 2026). "For this, we summarized gene expression patterns of CTTN and genes related to it, as well as other genes responsible for invasion mechanics of OSCC cancer cells." (PMID 37623256, 2023). "HBx supports the stability of cortactin CTTN and transcription factor PAX8, two proteins accepted as tumor markers overexpressed in various cancers." (PMID 35252867, 2022). "It has been reported that most of the 8 ARGs (VIM, UFM1, TSC2, SRC, MEFV, CTTN, CFTR and CDKN1A) are related to cancer." (PMID 35121801, 2022). "The role of CTTN ubiquitination was also explored in other pathways such as Wnt/β-catenin signaling and FBXL5 in cancer disease models." (PMID 35562995, 2022). "The inhibition of cortactin blocks the EMT, thereby preventing the proliferation, migration, and invasion of cancer cells." (PMID 33195233, 2020). "These regions host key cancer genes including PIK3CA, SOX2, EGFR, MYC, CCND1, CTTN, FHIT and CDKN2A/B." (PMID 32252688, 2020). "During extravasation, cancer cells form membrane protrusions enriched by MMP14 and cortactin characteristic for invadopodia." (PMID 31167468, 2019). "Specifically, CTTN, FAK, and ASAP1 have been demonstrated to be key regulators of tumor invasion, metastasis, and aggressive phenotypes in HNSCC and other cancers." (PMID 31731442, 2019). "We next evaluated by immunohistochemistry the expression of various SRC effectors, such as CTTN, FAK, and ASAP1, known to regulate tumor invasion, metastasis, and aggressive phenotypes in HNSCC and other cancers." (PMID 31731442, 2019). "Cancer-related genes including ANO1, CCND1, CTTN, FADD and ORAOV1 are involved in tumour cell proliferation, evasion of apoptosis, invasion, and migration." (PMID 28384287, 2017). "Finally, following the identification of cancer-related proteins CTTN, CSTB and CBS as novel proteomic targets of deoxyelephantopin, it is also tempting to speculate about potential biomedical application of synthetic analogues of this intriguing natural product as novel anticancer therapeutics." (PMID 27539788, 2016). "Overexpressed Kv10.1 controls cancer cell migration and proliferation by interactions with RAB proteins, cortactin (CTTN) and focal adhesion kinase (FAK) as well as through calcium signaling and an altered response to hypoxia." (PMID 27289382, 2016). "As CTTN and PBF colocalize at the leading edge of migrating cells, our data provides new mechanistic insights into blocking the movement of cancer cells by therapeutic targeting of this interaction." (PMID 27603901, 2016). "This non-muscle specific isoform was shown to directly interact with Cortactin that is also a SRC kinase dependent crucial factor for invadopodia formation and plays a role in aggressive cancers." (PMID 26334100, 2015). "Several known cancer-related genes, such as CCND1, FGF4, FGF3, and CTTN, have been mapped to the 11q13 chromosome region." (PMID 24930674, 2014).
cancer (continued). "Cortactin gene, CTTN (formerly designated EMS1), was identified to be amplified in several human cancers leading to cortactin overexpression." (PMID 23518204, 2013). "IHC examination showed cortactin expression was closely relative to TNM stage (AJCC/UICC), cancer embolus, and metastasis (P <0.01)." (PMID 23518204, 2013). "The probable target genes that are amplified and/or overexpressed in different cancers have been reported to include CCND1, FGF4, PPFIA1, CTTN and ORAOV1." (PMID 22920630, 2012). "Almost simultaneously, cortactin was cloned as the product of the CTTN gene (formerly EMS1), located in chromosomal region 11q13, which is frequently amplified in different human carcinomas." (PMID 22479425, 2012). "Some up-regulated genes such as ACVR1B, FYN and CTTN, and some down-regulated genes such as PTEN, are known to be correlated with cell migration and cancer metastasis." (PMID 21998723, 2011). "We also determined the effects of S405/418 cortactin phosphorylation on EGF-induced cell migration, adhesion and lamellipodia dynamics in carcinoma cells." (PMID 21079800, 2010). "Inhibition of carcinoma cell motility by MEK blockade and S405/418A expression indicates that S405/418 cortactin phosphorylation is important in promoting and maintaining cell migration." (PMID 21079800, 2010). "Cortactin, a regulator of ARP2/3-mediated actin polymerization, is known to contribute to tumour cell growth and cancer progression." (PMID 18268491, 2008). "Carcinomas with 11q13 amplification showed high protein expression levels in 8/8 cases for cyclin D1, 8/9 cases for FADD and 8/9 for cortactin." (PMID 18268491, 2008). "Furthermore, combination therapies targeting GPX4 and FAK/Src were found to enhance cancer cell death, and MDM2, ezrin, and cortactin were identified as potential ferroptosis inhibitor targets." (PMID 40164758, 2025). "In the present study, a simultaneous increase in the expression levels of NEK9, TRIM28 and CTTN was found in metastatic GC lesions compared with paired non-cancerous tissues and primary cancer lesions." (PMID 37443302, 2023). "A simultaneous increase in the expression levels of NEK9, TRIM28 and CTTN was found in metastatic GC lesions compared with paired non-cancerous tissues and primary cancer lesions via IHC and Multiplex IHC." (PMID 37443302, 2023). "In this study, we investigate the involvement of Shp1 in cancer invasion, report its localization at invadopodia, and define how Shp1 reduces ECM degradation through a direct, yet unknown, effect on cortactin phosphorylation at invadopodia." (PMID 34088320, 2021). "Differences in cell type, pathophysiologic state (e.g., cancer versus CSC exposure), or other experimental factors between these studies may account for this apparent discrepancy regarding the effect of CTTN expression level and apoptosis rates." (PMID 34831092, 2021). "Furthermore, it has been shown that cortactin overexpression promotes invadopodia function and MMP activity in many types of cancer cells." (PMID 32678085, 2020). "De-regulation of cortactin activity in the cell plays a crucial role in the development of various forms of cancer as well as non-malignant disorders such as inflammatory bowel disease." (PMID 31936446, 2020). "Indeed, our studies support this conjecture as regulating cortactin/CTTN levels in vitro had a direct impact on invasion and migration of cancer cells." (PMID 32709847, 2020). "Studies indicate that MAPK3, CTTN and PXN regulate chemo or TKIs-based targeted therapy in cancer." (PMID 29556515, 2018). "Deacetylation of cortactin by SIRT1 and HDAC6 promotes cancer cell migration and invasion, which also could be observed in p300-null cells." (PMID 29416718, 2018). "It has been demonstrated that in cancer cells, activation of hepatocyte growth factor receptor (HGFR, also known as MET), human epidermal growth factor receptor 2 (HER2, also known as ERBB2), and tyrosine kinases stimulates cortactin phosphorylation." (PMID 29152154, 2017).